IL11 (interleukin 11)
Diseases named in the same sentence as IL11 in open-access papers (continued):
Sharing a sentence is not in itself a finding about the gene and the disease.
colorectal cancer (31 papers, 2015 to 2025). A primary or metastatic malignant neoplasm that affects the colon or rectum. "AOM/DSS was administrated to induced colitis-associated colorectal cancer (CAC) in Il11−/− and wild-type (WT) mice." (PMID 37365574, 2023). "Based on the differentially expressed genes (DEGs), expression levels of IL-1β and IL-11, genes encoding for cytokines in the tumor microenvironment that promote colorectal cancer progression, were decreased by GLSF." (PMID 35692861, 2021). "In colorectal cancer, IL-6/IL-11-dependent STAT3 activation in cancer-associated fibroblasts promoted tumor development and also correlated with poor prognosis." (PMID 32865617, 2020). "Although IL-6 has been associated with many epithelial cancers, IL-11 acts as a more potent driver of colorectal cancers." (PMID 30736824, 2019). "High IL-11 expression was reported to be associated with poor differentiation, larger tumor size, lymph node metastasis and inferior overall survival of colorectal cancer patients." (PMID 30736824, 2019). "In colorectal cancer models driven by the loss of adenomatous polyposis coli gene, the up-regulation of gp130 expression leading to a heightened responsiveness to IL-6 and IL-11 also induces Yap1-dependent transcription." (PMID 37957015, 2024). "Il11ra1 or Il11 deletion attenuates the development of colitis-associated colorectal cancer." (PMID 33863879, 2021). "IL-11 may be involved in inflammatory responses and development of colitis-associated colorectal cancer." (PMID 29914371, 2018). "Higher IL-6, IL-8, and IL-11 levels were found to be associated with worse survival in patients with cancer, whereas elevated IL-10 and IL-6 levels might be markers of a favorable prognosis for colorectal cancer and lung cancer, respectively." (PMID 33912192, 2021). "Transmigration of the colorectal cancer cell line HT-29 was described earlier to be IL-11 dependent." (PMID 40895548, 2025). "IL‐11 is a member of the IL‐6 family of cytokines, involved in cancer progression across multiple cancer types such as colorectal cancer, gastric cancer, breast cancer, prostate cancer and endometrial cancer." (PMID 40673604, 2025). "-Tumor tissues from 7 colorectal cancer patients.-Analysis of IL-11 expression and p-STAT3 activation." (PMID 40650089, 2025). "This work supports the rationale that targeting gp130-dependent STAT3 signalling via the dual inhibition of IL-6 and IL-11 is a novel colorectal cancer treatment opportunity." (PMID 38600086, 2024). "MTERF3 plays an oncogenic role in colorectal cancer development by upregulating interleukin 6 and interleukin 11 to promote colorectal cancer cell growth and enhance radiotherapy resistance." (PMID 38589371, 2024). "We identified the presence of an intact gp130 signalling cascade in tumour organoids obtained from colorectal cancer patients by evaluating IL-6 and IL-11-dependent phosphorylation of STAT3." (PMID 38600086, 2024). "Excessive STAT3 signalling via gp130, the shared receptor subunit for IL-6 and IL-11, contributes to disease progression and poor survival outcomes in patients with colorectal cancer." (PMID 38600086, 2024). "Our observations demonstrate that dual targeting of IL-6 and IL-11 signalling represents a promising treatment strategy for colorectal cancer." (PMID 38600086, 2024). "IL11 correlates with progression of various cancers, including colorectal cancer, breast cancer, hepatocellular carcinoma, gastric carcinoma and renal cell carcinoma." (PMID 37365574, 2023). "In the present study we describe a hitherto unrecognized immune suppressing role of IL11 in initiation and progression of colorectal cancer based on IL11 knockout mice." (PMID 37365574, 2023). "In particular, IL-11, which is elevated in the human colorectal cancer microenvironment, mediates the radioresistance of cervical cancer cells via the PI3K-AKT-mTOR pathway." (PMID 35336821, 2022).
colorectal cancer (continued). "IL-11 has been shown to be elevated in colorectal cancer and in the exosomes of metastatic uveal melanoma and is associated with poor prognosis in melanoma." (PMID 36135194, 2022). "Human cancer database analysis reveals that the expression of genes enriched in IL-11+ fibroblasts is elevated in human colorectal cancer and correlated with reduced recurrence-free survival." (PMID 33863879, 2021). "Taken together, these results support bazedoxifene as a novel and effective therapeutic agent targeting IL-11/GP130 signaling for human colorectal cancer therapy." (PMID 30736824, 2019). "Nevertheless, there are few different theories concerning the role that IL-11 plays to promote colitis into colorectal cancer while the alleviating function of IL-11 in colitis has been detected." (PMID 29914371, 2018). "Meanwhile, IL-11 has emerged as an essential driver of colorectal cancer tumorigenesis." (PMID 38600086, 2024). "Additionally, MTERF3 was reported to promote cell growth and irradiation resistance by regulating interleukin (IL)-6 and IL-11 in colorectal cancer cells." (PMID 38397465, 2024). "This suggests that therapeutic inhibition of IL-6 and IL-11 signalling via inhibition of the gp130 receptor could be a beneficial treatment option for colorectal cancer patients." (PMID 38600086, 2024). "The activation of STAT3 by IL-6/IL-11 in fibroblasts promotes the development of colorectal cancer." (PMID 38054820, 2023). "Recent findings indicate that IL-11+ fibroblasts promote colorectal cancer and acute colitis." (PMID 36986706, 2023). "Furthermore, we confirmed that IL-11 protein was also expressed in tumour tissues of colorectal cancer patients." (PMID 28781374, 2015). "A study using a human cancer database found that genes enriched in IL-11+ fibroblasts were elevated in human colorectal cancer, and the high expressions of several of these genes correlated with a reduced disease-free survival rate in colorectal cancer patients." (PMID 37176567, 2023). "We confirmed expressions of both IL-11 and phosphorylated STAT3 in tumour tissues of colorectal cancer patients." (PMID 28781374, 2015). "Notably, the interleukin-6 (IL-6) family of cytokines, including IL-6, IL-11 and leukaemia inhibitory factor (LIF), directly activate STAT3 and contribute to the establishment and progression of colorectal cancer." (PMID 38600086, 2024).
colon carcinoma (27 papers, 2013 to 2025). "Our data suggest that the LRRK2 G2019S mutation enhances the production of IL-1β, IL-6 and IL-11 in the colon tumor microenvironment, thereby activating the NF-κB and STAT3 signaling pathways." (PMID 38607004, 2024). "We functionally confirmed this observation in IL11‐stimulated human SW480 colon cancer cells that harbor homozygous impairment mutations in the APC gene and therefore show aberrant WNT signaling." (PMID 30885958, 2019). "We have previously shown that BZA interferes with IL-6 and IL-11 signalling to suppress tumour growth in preclinical models of gastric and colon cancer." (PMID 38600086, 2024). "IL-11+ fibroblasts promote tumor progression by secreting IL-11 to activate colon tumor epithelial cells and colon fibroblasts." (PMID 38892375, 2024). "This study demonstrated that BZA directly binds to gp130, inhibiting IL-6 and IL-11 responses in several human colon cancer cell lines, xenograft, and patient-derived organoid models." (PMID 38600086, 2024). "High expression of TFRC promotes DSS-induced colonic epithelial cell death by activating the IL-6/IL-11-Stat3 pathway, which leads to mucosal injury and the occurrence of colon cancer." (PMID 37940859, 2023). "This study ascribes for a new immunomodulatory role for IL11 during tumor development that is amenable to anti-cytokine based therapy of colon cancer." (PMID 37365574, 2023). "MDSCs, cancer-associated fibroblasts (CAFs), and cancer cells upregulate IL-11 transcript levels during CRC development by a positive feedback loop between IL-11-secreting fibroblasts and epithelial colon tumor cells." (PMID 35884974, 2022). "Here the authors generate IL-11 reporter mice and characterize the origin and phenotype of inflammatory IL-11+ fibroblasts in colitis and colon cancer preclinical models." (PMID 33863879, 2021). "Expression of Il11 in colons from untreated mice was lower than that in colon tumor tissues from AOM/DSS-treated mice (0.002 in normal colon vs. 0.05 in tumor tissues)." (PMID 33863879, 2021). "Intriguingly, the relative area of IL-11+ cells and the IL-11 signaling intensity were increased in the stroma of advanced colon cancers compared with normal tissues, suggesting an intimate correlation between IL-11+ fibroblasts and CRC progression." (PMID 33863879, 2021). "Intriguingly, the expression of Il11ra in colon tumor organoids was higher than in colon epithelial organoids, suggesting that colon tumor cells can efficiently respond to IL-11 stimulation as the tumor develops." (PMID 33863879, 2021). "We generate Il11-Enhanced green fluorescence protein (Egfp) reporter mice and detect IL-11+ cells in the colonic tumor tissues of a CAC mouse model and ApcMin/+ mice." (PMID 33863879, 2021). "A previous study reported that high expression of IL11-responsive signature (IL11RS) genes induced in a human colon cancer cell line stimulated with IL-11 is correlated with reduced recurrence-free survival duration in CRC patients." (PMID 33863879, 2021). "Together, Il11ra expression in colonic epithelial cells increased along with tumor development, thereby enabling colon tumor cells to respond to IL-11 stimulation efficiently." (PMID 33863879, 2021). "Combined with miR-210-repressed hypoxia in obesity group, we inferred the inhibition of miR-210-hypoxia-IL11/IL11RA axis in obesity patients repressed the progression of colon cancer." (PMID 33197880, 2020). "When treated with IL-11 (10 ng/ml), the cell proliferation ability of three colon cancer cells was induced." (PMID 30736824, 2019). "To ascertain the biological importance of this observation in a pathologically relevant setting, we assessed the effects of bazedoxifene on IL11 signaling in patient‐derived samples of colon cancer cells grown as primary cultures." (PMID 30885958, 2019).
colon carcinoma (continued). "This not only explains a possible mechanism of oxaliplatin resistance acquired due to the IL-11 signaling but also provides a potential target in colon cancer prevention and therapy." (PMID 30736824, 2019). "Interleukin-11 (IL-11), a dominant IL-6 family cytokine, is involved in tumorigenesis, tumor progression and differentiation in colon cancer cells." (PMID 30736824, 2019). "We have demonstrated for the first time that the FDA-approved drug bazedoxifene can inhibit human colon cancer cells in vitro and in vivo by targeting IL-11/GP-130 signaling." (PMID 30736824, 2019). "In this study, we investigated the anti-cancer effect of bazedoxifene on human colon cancer cells in vitro and in vivo by blocking the IL-11/GP130 pathway." (PMID 30736824, 2019). "Several studies have emphasized the potential tumorigenic role of IL-11 in colon cancer as well as its potential role as a target in colon cancers." (PMID 30736824, 2019). "The WB results showed that IL-11 can induce the p-STAT3 expression in all three colon cancer cells, and this activation can be reversed by bazedoxifene." (PMID 30736824, 2019). "We combined bazedoxifene with oxaliplatin to suppress the elevated IL-11, and the combination of bazedoxifene and oxaliplatin worked synergistically to inhibit colon cancer cell viability." (PMID 30736824, 2019). "In colon cancer, the up-regulated IL-11 and IL-11R were also found to be highly expressed in samples of CRC patients." (PMID 30736824, 2019). "Our results showed that elevated IL-11 can reduce the efficacy of oxaliplatin and induce the resistance to oxaliplatin in colon cancer." (PMID 30736824, 2019). "For example, TMED3 can promote anti-metastatic WNT signaling in colon cancer cells, whereas it has been reported to promote IL11 signaling and tumor progression in liver cancer cells." (PMID 31253868, 2019). "To confirm that bazedoxifene treatment reduced the growth of colon cancer cells, we also derived organoids from tumors of ApcMin mice and observed that bazedoxifene treatment reduced IL11‐dependent organoid growth (Fig EV3B)." (PMID 30885958, 2019). "All these results confirmed that bazedoxifene exerted its inhibitory role in colon cancer cells through inhibition of the IL-11/GP130/STAT3 signaling pathway." (PMID 30736824, 2019). "In conclusion, our results indicate that FDA-approved bazedoxifene, as a novel GP130 inhibitor that blocks IL-11 signaling and can be repurposed for the treatment of colon cancer." (PMID 30736824, 2019). "IL-11, a member of the IL-6 family of cytokines, has been recently identified as potentially the most important cytokine in promoting colon cancer through exclusive utilization of GP130 homodimers when bound to its receptor, IL-11R." (PMID 30736824, 2019). "IL-11 signaling is a very important and novel potential therapeutic target for the treatment of gastrointestinal cancers, including colon cancers." (PMID 30736824, 2019). "Bazedoxifene inhibits phosphorylation of signal transducer and activator of transcription 3 (p-STAT3) and its nuclear translocation induced by IL-11 in colon cancer cells." (PMID 30736824, 2019). "We then exploited patient‐derived human colon cancer organoids grown in 3D cultures in the presence of IL11." (PMID 30885958, 2019). "Our data comprehensively extend these observations and demonstrate significant anti‐tumorigenic effects of bazedoxifene in multiple IL11‐dependent and immune‐competent models of spontaneous gastric, intestinal, and colon cancer." (PMID 30885958, 2019). "Hypoxia can induce IL-11 expression in the human colon cancer cell line, HCT116, through cooperative interactions between HIF-1α and AP-1 within the IL-11 promoter." (PMID 30197757, 2018). "Here we investigated IL-11 gene expression in seven primary tumour tissues of patients with colon cancer." (PMID 28781374, 2015).
colon carcinoma (continued). "Here we demonstrated that IL-11 was produced as a soluble factor in the tumour microenvironment of patients with colon cancer and promoted the differentiation of immune cells into functional MDSCs." (PMID 28781374, 2015). "Genetic downregulation of p38α in AOM/DSS-induced mouse colon tumors reduces tumor growth, which correlates with reduced levels of IL-6, IL-11, CXCL-1 and CXCL-2." (PMID 25890501, 2015). "As in the early phase of DSS induction, colonic tumor IL-6 (P<0.05) and possibly IL-11 (P = 0.07) mRNA expression was higher in Iron/DSS compared with Control/DSS mice but not TNF or IFNγ." (PMID 24223168, 2013). "IL-11 efficiently activated IL-11+ colonic fibroblasts and colon tumor organoids." (PMID 33863879, 2021). "Notably, cells expressing both EGFP and IL-11 were easily detected in colon tumor tissues of AOM/DSS-treated Il11-Egfp reporter mice." (PMID 33863879, 2021). "Thus, our results suggest that IL-11+ fibroblasts activate both colon tumor epithelial cells and colon fibroblasts through IL-11 secretion, thereby contributing to tumor progression." (PMID 33863879, 2021). "To detect the interplay between IL-11+ fibroblasts and colon tumor cells, we tested whether IL-11 induced the activation of colon tumor cells." (PMID 33863879, 2021). "Together, our present results demonstrate that tumor cells induce IL-11+ fibroblasts and that a feed-forward loop between colon tumor epithelial cells and IL-11+ fibroblasts via secretion of IL-11 may contribute to tumor development." (PMID 33863879, 2021). "To test whether fibroblasts with gene signatures similar to that of IL-11+ fibroblasts appear in tumor tissues in mouse and human colon cancers, we examined gene expression profiles of tumor tissues." (PMID 33863879, 2021). "Collectively, the gene expression profiles of IL-11+ fibroblasts present in DSS-induced colitis may at least partly overlap those of colon tumors in mice treated with AOM/DSS." (PMID 33863879, 2021). "The MTT array showed that colon cancer cells inhibited by bazedoxifene could be partially rescued by excessive administration of IL-11." (PMID 30736824, 2019). "Therefore, we selected bazedoxifene, which can directly target IL-11 in a computational model and has inhibitory effects on colon cancer." (PMID 30736824, 2019). "Since activated STAT3 and IL-11 were found to be overexpressed and promote tumorigenesis in most colon cancers, we hypothesized a potential inhibitory role of bazedoxifene in colon cancers." (PMID 30736824, 2019). "IL-11 signaling has been recently identified as a potential therapeutic target in colon cancer." (PMID 30736824, 2019). "Increased intratumoral IL-6 and possibly IL-11 expression suggested that Stat3 activation may contribute to the development of dietary iron induced-colonic tumors." (PMID 24223168, 2013). "Increased intratumoral IL-6 and possibly IL-11 expression suggested that dietary iron may promote colonic tumor development via a Stat3-mediated pathway." (PMID 24223168, 2013). "This provided the evidence that colon cancer may be treated by targeting IL-11." (PMID 30736824, 2019). "We then investigated whether excessive IL-11 could induce drug resistance to oxaliplatin, and the results showed that an addition of IL-11 partially reversed the efficacy of oxaliplatin-mediated inhibition of cell viability in colon cancer cells." (PMID 30736824, 2019). "IL11 has not been previously associated with AHR but is known to suppress CD4+T cells mediated anti-tumor immunity, and the IL11/STAT3 inhibition increased MHC-I expression and T cell infiltration in colon cancers." (PMID 40283908, 2025). "We found that the expression levels of some genes enriched in IL-11+ fibroblasts, including Wnt5a, Mmp13, Timp1, Il1rl1, Cxcl5, Saa3, Inhiba, Ascl4, and Tnfrsf11b, were elevated in mouse AOM/DSS-induced colon tumor tissues." (PMID 33863879, 2021).